Y_RNA (Y RNA )
Gene: Miscellaneous RNA gene on chromosome 6 (34,821,445 to 34,821,542, forward strand). Ensembl gene ENSG00000206717.
Homologues: Orthologues: chimpanzee Y_RNA (99% identical), guinea pig Y_RNA (95% identical), macaque Y_RNA (95% identical). Paralogues in human: RNY3 (93% identical), Y_RNA (92% identical), Y_RNA (91% identical), RNY3P1 (90% identical), Y_RNA (90% identical), Y_RNA (89% identical), Y_RNA (88% identical), RNY3P11 (87% identical), RNY3P9 (87% identical), Y_RNA (87% identical), RNY3P14 (86% identical), RNY3P16 (86% identical), and 95 more.